ACE (angiotensin I converting enzyme)
Diseases named in the same sentence as ACE in open-access papers (continued):
Sharing a sentence is not in itself a finding about the gene and the disease.
Hypertension (continued). "Notably, most pathology labs measure ACE activity, which is affected by ACE inhibitor (ACEI) drugs used in hypertension, whereas ACE protein levels remain unaffected." (PMID 38611622, 2024). "ACE inhibitors and AT1R antagonists, often prescribed for conditions like hypertension, could potentially mitigate severe COVID-19 infection in dementia patients by preventing the cytokine storm and reducing the risk of end organ damage." (PMID 38247982, 2024). "The insertion/deletion polymorphism of angiotensin-converting enzyme (ACE) gene phenomenon and its relationship with essential hypertension has not been explored within the Ghanaian population." (PMID 39666621, 2024). "The well-known small molecule ACE inhibitors, captopril, lisinopril, and enalaprilat, have proved to be clinically effective in the treatment of hypertension and congestive heart failure, but they are not inhibitors of ACE2." (PMID 39273366, 2024). "CCBs are first-line stand-alone or combination medications for treating high blood pressure in patients without significant renal involvement (ACE inhibitors and ARBs are renoprotective)." (PMID 39100000, 2024). "To summarize, the EO of black pepper may have potential in preventing and/or managing hypertension and T2DM, due in part to its phenolic content, the inhibition of α-glucosidase, α-amylase, and ACE activities and antioxidant activity." (PMID 38003691, 2023). "Angiotensin-converting enzyme (ACE) is the vital enzyme involved in the formation of bioactive ANG II, which is an endogenous potent vasoconstrictor responsible for the pathogenesis of hypertension." (PMID 37153428, 2023). "In practice, angiotensin-converting enzyme inhibitors (ACE inhibitors) or angiotensin receptor blockers (ARBs) are the first line of agents in patients with hypertension and DKD, even in the absence of proteinuria." (PMID 37834846, 2023). "Treatment with ACE inhibitors (ACEi) and Ang II receptor blockers (ARB), which are commonly used to manage hypertension, could be beneficial in COVID-19 by potentially mitigating the harmful effects of an imbalanced RAS." (PMID 37626615, 2023). "Therefore, we attempted to provide evidence of the effect of genetic variation of the rs4331 ACE gene and rs2074192 ACE2 gene on the severity of COVID-19 in COVID-19 patients with hypertension comorbidity." (PMID 37667339, 2023). "This is irrespective of the common BP control agents (TD, CCB, and ACE inhibitors) used by patients to treat hypertension, with over half being on tri-therapy, over two-thirds having low to moderate treatment adherence, and almost none with high adherence." (PMID 37893857, 2023). "ACE inhibitors do not depend on blood sugar levels and hence are the first choice for diabetic patients suffering from hypertension." (PMID 37389408, 2023). "PCR: Polymerase Chain Reaction, BMI: Body Mass Index, %SpO2: Percent Saturation of Peripheral Oxygen, HTN: Hypertension, COPD: Chronic Obstructive Pulmonary Disease, ACE Hx: History of Angiotensin-Converting Enzyme inhibitor use, ARB Hx: History of Angiotensin II Receptor Blocker use, N: Number." (PMID 38022268, 2023). "Moreover, exosomes from normotensive WKY rats reduced vascular angiotensin‐converting enzyme (ACE) expression and attenuated vascular remodelling and hypertension in SHR rats via mechanisms dependent on miR155‐5p." (PMID 35306667, 2023). "A retrospective study in China showed that COVID-19 patients with hypertension without ACE inhibitors and ARBs had reduced mortality (HR = 0.42; 95% CI: 0.19, 0.92; P = 0.03)." (PMID 37425387, 2023). "Angiotensin-converting enzyme inhibitors (ACEIs), which block the action of ACE-1, and angiotensin receptor blockers (ARBs), which block the action of angiotensin II at AT1 receptors, are two RAAS inhibitors widely used to treat hypertension, heart failure, and renal failure." (PMID 37593954, 2023).
Hypertension (continued). "Hypertension is normally accompanied by many comorbidities that are major factors for disease severity, and there is little evidence of ACE inhibitors influencing tissue expression or activity of ACE2 in humans." (PMID 36948200, 2023). "ACE is involved in, among many other diseases, ASCVD, hypertension and heart failure." (PMID 37877017, 2023). "This protective arm is characterized by ACE2/Ang 1-7/MasR and Ang 1-9 that largely counteracts the classic arm of the RAAS mediated by ACE/Ang II/AT1R/aldosterone and plays an important role in the prevention of inflammation, oxidative stress, hypertension, and cardiovascular remodeling." (PMID 37959338, 2023). "Unlike antihypertensive drugs, food-derived ACE-inhibitory peptides have few side effects and a significant utilization value for people with hypertension and cardiovascular disease." (PMID 37761171, 2023). "Some studies have shown that soybean peptides have many functions, including hypocholesterolemia, outcomes against cancer, angiotensin-converting enzyme (ACE), hypertension, and regulation of the immune system, while additional uses and benefits are constantly being uncovered." (PMID 37396130, 2023). "SARS-CoV-2 determines a disruption of this ACE/ACE2 balance and activation of RAAS, which ultimately leads to the progression of COVID-19, particularly in comorbid patients (cardiovascular disease, hypertension, diabetes mellitus)." (PMID 37189632, 2023). "Activation of the ACE/Ang II/AT1R axis induces endothelial dysfunction and vascular remodeling specifically in small vasculature (resistance arteries) which are the key step in development of vascular resistance, a typical feature of hypertension." (PMID 37854465, 2023). "The radiation-induced changes in ACE and ACE2 expression are similar to findings in a hypertension rat model, where male rats were observed to have an imbalance in the relative levels of lung ACE and ACE2 levels pathways favoring activation of the proinflammatory ACE/AngII signaling pathway." (PMID 37275232, 2023). "We found that in spontaneously hypertensive rats (SHRs), a model mimicking human essential hypertension, MLN induced detrimental effects on adiposity, the function of small arteries and angiogenesis, as well as a reduction in the ACE inhibitor (ACEI)-induced hypotensive effect." (PMID 37875978, 2023). "Furthermore, long-term studies of sACE2 levels are required in at-risk populations (e.g., those with and without hypertension and chronic kidney disease) and in patients receiving treatments that may affect sACE2 activity or concentration (i.e., ACE inhibitors or angiotensin receptor blockers)." (PMID 35453934, 2022). "Although there are many reviews that cover the inhibition of ACE as a possible mechanism of food-derived antihypertensive peptides, none has covered the relationship between gut microbiota, hypertension, and food peptides, hence the subject of this paper." (PMID 36557936, 2022). "We assessed whether the expression levels of ACE, ChAT, AT1, and AT2 in hippocampus tissue were affected by hypertension in adult rats." (PMID 35528844, 2022). "In addition, plasma levels of angiotensin-converting enzyme (ACE) were found to be increased in SHR rats following exposure to Hg, which can lead to vasoconstriction and hypertension." (PMID 36232403, 2022). "In addition to diseases such as hypertension, treatment with inhibitors of the renin-angiotensin-aldosterone system (RAAS) causes an upregulation of ACE2 expression; this has led to the hypothesis that ACE inhibitor therapy may predispose patients to more severe COVID-19 courses." (PMID 35448480, 2022). "Central to the pathology of hypertension and its complications is the renin-angiotensin-aldosterone system (RAAS), and the principal component of the RAAS is the angiotensin I-converting enzyme (ACE)." (PMID 35804705, 2022).
Hypertension (continued). "The increase in blood pressure was attenuated by treatment with an ACE inhibitor, suggesting that an over-activated renin/angiotensin system may be a key mechanism in DDT-induced hypertension." (PMID 35273934, 2022). "Lisinopril is a non-sulfhydryl angiotensin-converting enzyme (ACE) inhibitor widely prescribed for treating patients suffering from hypertension and congestive heart failure, both tightly related to coronary heart disease." (PMID 35656292, 2022). "Extensive preclinical data support the potential use of angiotensin II receptor blockers (ARBs) and angiotensin I converting enzyme (ACE) inhibitors, two common classes of medications FDA approved for the management of hypertension, as antineoplastic agents in PC." (PMID 35130875, 2022). "Upregulation of intrarenal angiotensinogen and ACE expression and down-regulation of ACE2 and MasR gene expression contributed to obtaining a high AngII/Ang 1-7 ratio, which facilitated the development of hypertension." (PMID 36148474, 2022). "Binding of BAC with ACE prompted us to examine whether BAC affects the expression of ACE and ACE2 in HUVECs, which are model cells for studying hypertension." (PMID 35359841, 2022). "ACE is an integral part of the renin-angiotensin system (RAS) system, which can catalyze angiotensin I (Ang I) into Ang II with high-strength vasoconstriction activity, thereby inducing hypertension." (PMID 35600813, 2022). "Taking EH as the dependent variable, multiple-factor logistic regression analysis was used to analyse the influence of the interactions between ACE, ACE2, CYP11B2 and noise on EH based on the multiplicative model after adjustment for BMI, family history of hypertension, TG, TC and other confounders." (PMID 35130889, 2022). "Taken together, BAC could directly inhibit the activity and protein expression of ACE and increased the activity of ACE2 to attenuate hypertension." (PMID 35359841, 2022). "ACE and ACE2 are the main regulatory enzymes in RAS and the key targets for anti-hypertension." (PMID 35359841, 2022). "The top-8 ranked features from the XGB feature ranking technique achieved the best performance with 90% accuracy in 10-fold cross-validation, and the ranked variables were hypertension, duration of IDDM, drinking, triglycerides, ACE inhibitors, LDL, age, and smoking." (PMID 36143293, 2022). "Mice expressing ACE exclusively in the kidney tubules but not in other tissues displayed hypertension when infused with Ang I." (PMID 35710133, 2022). "We found an important number of patients using diuretics (n = 125), ACE inhibitors and ARB blockers (n = 163), and NSAIDs (n = 43) who had ARF The most frequent comorbidities of the patients with ARF were hypertension, cardiac disorders, depression and anxiety, hyperlipidemia, and pain." (PMID 36003521, 2022). "For the management of hypertension in the HCV patient, Angiotensin-converting enzyme (ACE) inhibitors should be given only as needed and preferably in combination with sofosbuvir/velpatasvir (SOF/VEL) and not in combination with glecaprevir/pibrentasvir (GLE/PIB)”; “22." (PMID 36498521, 2022). "Two classes of RAS blockers, i.e., angiotensin-converting enzyme (ACE) inhibitors (e.g., enalapril) and AT1 receptor antagonists (e.g., losartan), serve as first-line drugs for the treatment of essential hypertension according to the guidelines of American and European heart societies." (PMID 35563848, 2022). "ACE is a key mediator in the RAAS that regulates blood pressure by converting angiotensin I to the potent vasoconstrictor angiotensin II, which plays a central role in the pathogenesis of essential hypertension." (PMID 36364047, 2022). "DM, diabetes mellitus; HTN, hypertension; CAD, coronary artery disease; DL, dyslipidemia; HF, heart failure; COPD, chronic obstructive pulmonary disease; CKD, chronic kidney disease; ACE, angiotensin-converting enzyme inhibitors; ARB, angiotensin receptor blockers." (PMID 34812311, 2021).
Hypertension (continued). "Studies found that ACE/ACE-2 ratios were significantly higher in patients with hypertension than in those without." (PMID 34481475, 2021). "In kidneys, increases in ACE/ACE2 ratio induced via the Ang II-AT1R axis have a significant influence on the development of severe renal damage and disease progression, such as diabetes, nephropathy and hypertension in humans." (PMID 34385922, 2021). "ACE-inhibitor therapy, although routinely used in the treatment of hypertension and HF, does not completely block Ang-II production, and some patients can often show elevated Ang-II levels despite ACE-inhibitor therapy." (PMID 34490381, 2021). "Researchers were able to investigate the interplay between angiotensin-converting enzyme (ACE) genotypes and childhood obesity for the development of adult high blood pressure and hypertension across three cross-prospective cohort studies, including 4,835 participants." (PMID 34912641, 2021). "This work has demonstrated an efficient affinity purification method for ACE inhibitors from complex protein mixtures, and the purified peptide KNFL may have potential applications in functional foods or as drugs for hypertension treatments." (PMID 33807119, 2021). "Patients with hypertension were treated with angiotensin-converting enzyme (ACE) inhibitors without B-blocker therapy." (PMID 33809001, 2021). "The angiotensin-converting enzyme (ACE) blockers ramipril, captopril, and lisinopril, also known for their relatively low side effects, are used worldwide for the treatment of chronic illnesses such as hypertension and diabetes." (PMID 34440554, 2021). "Levels of antihypertensive use were generally similar in participants with and without physiological hypertension, except for higher use of ACE inhibitors (37.0% vs 29.3%) in supine normotensives compared to supine hypertensives." (PMID 34043698, 2021). "RAAS blockers, as ACE inhibitors (ACEI) and angiotensin II receptor blockers (ARBs), are worldwide used for effectively reducing systemic vascular resistance in patients with hypertension, heart failure and chronic renal disease." (PMID 34925477, 2021). "The angiotensin-I-converting enzyme (ACE, EC 3.4.15.1) is a dipeptidyl carboxypeptidase that belongs to the zinc metalloenzyme family and plays a crucial role in blood pressure control via monitoring and attenuating hypertension." (PMID 34940650, 2021). "ACE2, unlike ACE, is not inhibited by ACE inhibitors at the doses used in humans during the treatment of arterial hypertension." (PMID 33925881, 2021). "Angiotensin converting enzyme (ACE) inhibitors (ACEi), such as enalapril, lisinopril and ramipril, and angiotensin receptor blockers (ARB) such as losartan, telmisartan and valsartan are widely used to treat hypertension." (PMID 33613842, 2021). "The ACE2/Ang‐(1‐7)/MasR axis is a potential target for combating the negative effects of the ACE/Ang II/AT1R axis on hypertension, and ACE2 plays a key role in this axis." (PMID 33443816, 2021). "Regarding hypertension and antihypertensive treatment, there is need for on-treatment more powerful trials on ACE inhibitors versus ARBs, and BP control versus no control, as well as post-COVID sequelae." (PMID 33687179, 2021). "However, current evidence on COVID-19 and ACE inhibitors or ARB medication is controversial, and the correlation of ACE2, DM, hypertension, and severity of COVID-19 cannot be as simple as it seems." (PMID 34205044, 2021). "Angiotensin-I converting enzyme inhibitory peptides derived from food sources represent an effective way to treat hypertension without incurring unacceptable side effects." (PMID 34568409, 2021). "It is reported that, ACE blockers, Ang II receptor blockers (ARBs) are supportive therapy to inhibit the Ang II-induced hypertension, kidney function and lung congestion, but these are not direct therapy against viral infection." (PMID 33442728, 2021).
Hypertension (continued). "The other 13 (5 with hypertension on calcium channel blockers and 8 without hypertension) patients did not use ARBs or ACE inhibitors." (PMID 33992075, 2021). "In stressed heart, ACE is up-regulated inversely to ACE2, leading to an imbalance in the ACE/ACE2 ratio, increased production of Ang II, and disturbance in RAAS homeostasis, which promote Ang II-induced hypertension, cardiac hypertrophy, and fibrosis." (PMID 34385922, 2021). "Many patients with hypertension and cardiovascular comorbidities are commonly prescribed with anti-hypertensive RAAS inhibitors, such as the angiotensin-converting enzyme inhibitors (ACE-Is) and angiotensin II receptor blockers (ARBs)." (PMID 34880395, 2021). "ACE inhibitors (ACEI), angiotensin II AT1 receptor blockers (“sartans”), calcium channel blockers, diuretics (thiazides) and beta-blockers are indicated for the treatment of RAS-related hypertension." (PMID 33799957, 2021). "The results were supported by other studies showing that daily administration of captopril (5 mg/kg) could reduce hypertension and cardiac remodeling in rats with long-term exposure to l-NAME via inhibition on ACE." (PMID 34925007, 2021). "More frequent use of angiotensin-converting enzyme inhibitor (ACE), older age, and higher systolic and diastolic blood pressure values were more prevalent among patients with uncontrolled hypertension relative to patients with controlled hypertension (p<0.05)." (PMID 34909974, 2021). "CIHH decreased high blood pressure in SHR, possibly by inhibiting RAS activity, downregulating the ACE-Ang II-AT1 axis and upregulating the ACE2-(Ang1-7)-Mas axis, which resulted in antagonized vascular remodeling and fibrosis, reduced inflammation, and enhanced vascular relaxation." (PMID 33841179, 2021). "In conclusion, CIHH decreased high blood pressure in SHRs, which may have occurred by inhibiting RAS activity, downregulating the ACE-Ang II-AT1 receptor axis, and upregulating the ACE2-(Ang1–7)-Mas receptor axis." (PMID 33841179, 2021). "This synergistic regulation is observed in renal biopsies from humans, in which the ACE to ACE2 ratio is significantly higher in subjects with hypertension than in subjects without hypertension." (PMID 33329052, 2020). "Orally active ACE inhibitors are effective antihypertensive agents, not only in high-renin hypertension but also in clinical and experimental models that do not involve the systemic RAS." (PMID 33126450, 2020). "Basic drugs for hypertension treatment were also lacking with only 7% of facilities having all the essential medicines, 21% with ACE inhibitors, 37% with thiazide diuretics, and 16% with beta blockers." (PMID 31945075, 2020). "Traditional anti-hypertension drugs, such as angiotensin II receptor blockers (ARBs) or angiotensin-converting enzyme (ACE) inhibitors, are often not suitable for preconception or pregnant women." (PMID 32577117, 2020). "This method may be an innovative method for assessing the effect of RNA interference or therapeutic effects of ACE inhibitors, providing new ideas and targets for the role of RAS in the research and treatment of hypertension and cardiovascular remodeling." (PMID 32983648, 2020). "In a study of 5,700 patients hospitalized with COVID-19 in the New York City area, the mortality rates for patients with hypertension not taking an ACE inhibitors or ARBs at admission, taking an ACE inhibitor, or taking an ARB were comparable." (PMID 33195473, 2020). "Many comorbidities in the elderly such as hypertension, diabetes and CKD were treated with ACE inhibitors and angiotensin II receptor blockers, which would upregulate the ACE2 receptor, thereby increasing the risk of SARS-CoV-2 infection and the risk of disease." (PMID 32805730, 2020).